AHRR (aryl hydrocarbon receptor repressor)
Description:
Mediates dioxin toxicity and is involved in regulation of cell growth and differentiation. Represses the transcription activity of AHR by competing with AHR for heterodimer formation with ARNT and subsequently binding to the xenobiotic response element (XRE) sequence present in the promoter regulatory region of a variety of genes. Represses CYP1A1 by binding the XRE sequence and recruiting ANKRA2, HDAC4 and/or HDAC5. Autoregulates its expression by associating with its own XRE site. [Isoform 1]: Represses AHR transcription activity. Also represses transcription mediated by HIF1A and EPAS1/HIF2A but does not repress NR1I2/PXR or ESR1 transcriptional activities. [Isoform 2]: Does not repress AHR transcription activity.
Synonyms: bHLHe77; KIAA1234; AHH; AHHR
Gene: Protein-coding gene on chromosome 5 (320,682 to 438,291, forward strand). Ensembl gene ENSG00000063438.
Subcellular location: Cytoplasm; Nucleus
Subcellular location (Human Protein Atlas): Nucleoplasm; Cytosol
Genetic constraint (gnomAD): Loss-of-function variants: 28 observed, 42.78 expected, observed/expected ratio (o/e) 0.65, 90% interval 0.48 to 0.9. The upper end of that interval is the gene's LOEUF score, 0.9, which puts it in group 3 of 6, group 1 being the genes least tolerant of losing a copy. Missense variants: 990 observed, 922.14 expected, observed/expected ratio (o/e) 1.07, 90% interval 1.02 to 1.13. Synonymous variants: 434 observed, 382.52 expected, observed/expected ratio (o/e) 1.13, 90% interval 1.05 to 1.23.
Homologues: Orthologues: chimpanzee PDCD6 (98% identical), macaque AHRR (93% identical), dog AHRR (66% identical), pig AHRR (66% identical), mouse Ahrr (61% identical), guinea pig AHRR (59% identical), tropical clawed frog ahrr (44% identical), zebrafish ahrrb (29% identical), Drosophila melanogaster ss (22% identical), Caenorhabditis elegans ahr-1 (19% identical), zebrafish ahrra (16% identical). Paralogues in human: AHR (29% identical).
Diseases named in the same sentence as AHRR in open-access papers:
AHRR is named in the same sentence as 82 diseases in open-access papers, as found by Europe PMC text mining. Sharing a sentence is not in itself a finding about the gene and the disease. The quoted sentences say what the papers report.
lung carcinoma (59 papers, 2015 to 2026). "Our findings include the aryl hydrocarbon receptor repressor (AHRR), which has been linked to an elevated risk of lung cancer." (PMID 39164771, 2024). "AHRR hypomethylation has been associated with low lung function, increased lung cancer risk andmortality, and with smoking related morbidity and mortality." (PMID 37696456, 2023). "In our previous study, the risk of COPD and lung cancer was 52% and 65% higher, respectively, for every 10 percentage points lower AHRR methylation." (PMID 36621758, 2023). "Among the selected smoking-related CpG sites, three were previously identified as being associated with lung cancer risk (AHRR-cg0557921, F2RL3-cg03636183 and ALPPL2-cg01940273)." (PMID 35595947, 2022). "In the hypothetical case where a risk prediction test for lung cancer based on AHRR methylation exists, should the incidental finding of an increased risk cardiovascular disease be communicated?" (PMID 35337378, 2022). "Transforming growth factor beta 1 (TGFβ1), associated with inflammation and lung cancer risk and the smoking-related differentially methylated gene Aryl-hydrocarbon receptor repressor (AHRR) are likewise modifiers of CF lung disease." (PMID 34415821, 2022). "What is more, smoking-associated DNA methylation changes (e.g., AHRR or F2RL3 genes) have been described to predict risk of lung cancer." (PMID 35337378, 2022). "A large number of studies had discussed the association of the genetic polymorphism of AHR, ARNT, AHRR genes and human diseases such as Crohn’s disease (CD), lung cancer, male infertility, and autoimmune diseases." (PMID 35309329, 2022). "AHRR, an Aryl hydrocarbon receptor repressor, a known tumor suppressor has been associated with smokers in lung cancer patients in an epigenetic manner." (PMID 34796107, 2021). "We report for the first time that fluorene exposure is associated with the DNA hypomethylation of F2RL3 and AHRR, prospective markers for lung cancer, in the chimney sweeps." (PMID 32385190, 2020). "Increasing fluorene exposure, among chimney sweeps, was associated with lower DNA methylation of F2RL3 and AHRR, markers for increased lung cancer risk." (PMID 32385190, 2020). "The mechanism underlying the relationship between AHRR cg05575921 methylation and lung cancer is unclear." (PMID 32736658, 2020). "It captures well the known time- and dose-varying causal association of smoking with lung cancer (OR > 4) and cardiovascular diseases, and is correlated with known smoking-induced demethylation at the AHRR locus." (PMID 32529581, 2020). "In recent studies, the hypomethylated CpG sites in the AHRR gene in pre-diagnostic peripheral blood samples were reported to be associated with lung cancer risk." (PMID 32928150, 2020). "Findings in CCHS were supportive of a causal effect of AHRR methylation on lung cancer [HR = 0.30 (95% CI = 0.10, 1.00) per SD], but in two-sample MR this site was not causally implicated [OR = 1.00 (95% CI = 0.83, 1.10) per SD increase]." (PMID 31549173, 2019). "Blood AHRR methylation (especially at cg0557592) is inversely associated with both smoking and lung cancer." (PMID 31060609, 2019). "Hypomethylation of aryl hydrocarbon receptor repressor (AHRR) especially at cg05575921 is associated with smoking and lung cancer." (PMID 31060609, 2019). "Association between AHRR (cg05575921) methylation extent (%) and reduced survival (from all-cause mortality) among 465 patients with lung cancer." (PMID 30730943, 2019). "Among the discovered loci, CpGs in the F2RL3 and AHRR were repeatedly associated with smoking and the risk of developing lung cancer." (PMID 31450665, 2019). "Among former and current smokers, there was an association across ranked quintiles of lower AHRR (cg05575921) methylation extent with higher incidence of lung cancer (p=3×10−11 and p=1×10−7, log-rank trend test), whereas this was not seen among never smokers." (PMID 28100713, 2017).
lung carcinoma (continued). "The logistic multivariate analysis demonstrated that AHRR methylation was significantly associated with the risk of lung cancer (OR = 0.960, 95% CI = 0.930–0.990, P = 0.011)." (PMID 28453567, 2017). "The genetic polymorphisms in AHRR have been shown to be risk factors for cancer via ameliorating this AhR repressor activity, and DNA methylation change in AHRR has been linked to smoking exposure and lung cancer." (PMID 28056099, 2017). "Our previous work using candidate gene approaches has demonstrated the potential use of mortality-related DNAm markers, such as F2RL3 and AHRR, for lung cancer and CVD risk prediction." (PMID 28303888, 2017). "Logistic multivariate analysis showed that AHRR methylation is significantly associated with the risk of lung cancer (OR = 0.96, P = 0.011)." (PMID 28453567, 2017). "Within a large group of smokers with a 6-year a priori risk of lung cancer above the current cut-off for lung CT scan, AHRR cg05575921 methylation extent separated individuals into a very low, an intermediate and a high-risk group." (PMID 28100713, 2017). "Among these regulatory factors, we identify AHR, the aryl hydrocarbon-receptor which controls a healthy immune response in the lung epithelium and whose repressor, AHRR, has recently been implicated in smoking-mediated lung cancer." (PMID 29262847, 2017). "More recent studies have shown that many of the top-ranked smkDMCs (e.g. this includes CpGs mapping to the aryl hydrocarbon-receptor repressor [AHRR] locus) predict the future risk of lung cancer and all-cause mortality." (PMID 29262847, 2017). "PAHs induced hypomethylation of F2RL3 and AHRR, epigenetic changes linked to lung cancer risk." (PMID 39440184, 2024). "It has been reported that as much as 32% of the smoking-induced risk for lung cancer may be mediated through AHRR hypomethylation, and AHRR is downregulated in several types of malignancies, including lung cancer." (PMID 36621758, 2023). "Furthermore, past studies have found that tobacco smoke often leads to the hypomethylation of critical genes, such as AHRR—which is highly implicated in lung cancer risk." (PMID 34439379, 2021). "Moreover, chimney sweeps showed the hypomethylation of F2RL3 and AHRR—prospective markers for increased risk of lung cancer, with increasing fluorene metabolite concentrations." (PMID 32385190, 2020). "Prior studies have shown that AHRR (cg05575921) hypomethylation may be a marker of smoking, lung cancer risk and potentially lung cancer survival (in some lung cancer subtypes)." (PMID 30730943, 2019). "Thus, we examined the association between AHRR (cg05575921) hypomethylation in bisulfite treated leukocyte DNA and survival among lung cancer patients from the Lung Cancer Study (LUCAS), also referred to as the Copenhagen study." (PMID 30730943, 2019). "Along with prior studies showing association between AHRR hypomethylation and increased lung cancer risk, these findings suggest that smoking-associated methylation changes are more involved in initiation than progression of lung cancer." (PMID 30730943, 2019). "It is unknown if AHRR (cg05575921) hypomethylation is associated with reduced survival among lung cancer patients." (PMID 30730943, 2019). "Although AHRR methylation might be useful in assessing lung cancer risk in a population of smokers, our results suggest that it cannot identify lung cancer patients with poor prognosis independently of other commonly used prognostic factors." (PMID 30730943, 2019). "It is unclear if AHRR methylation in itself is a cause of increased lung cancer risk." (PMID 30730943, 2019). "Importantly, AHRR (cg05575921) methylation extent has been linked to lung cancer risk, and seems to be a more accurate risk estimator of lung cancer than self-reported smoking." (PMID 30730943, 2019).
lung carcinoma (continued). "Using the published lung cancer risk prediction model, the 6-year lung cancer risk was calculated: we then explored if AHRR (cg05575921) methylation extent improves lung cancer risk prediction among high-risk smokers, and thus helps to decide who should be offered lung CT scans." (PMID 28100713, 2017). "Some studies have even suggested that hypomethylation at the AHRR locus (and other top-ranked smkDMCs) may be causally involved in mediating the risk of smoking on lung cancer." (PMID 29262847, 2017). "Among smokers at high risk of lung cancer, and eligible to screening with CT scan, AHRR (cg05575921) methylation extent could help to identify a subgroup with the potential most benefit from a lung CT scan." (PMID 28100713, 2017). "However, the biological mechanism(s) linking hypomethylation of the AHRR and other top-ranked smkDMCs to lung cancer risk remain elusive." (PMID 29262847, 2017). "A key finding has emerged around the AHRR gene: the methylation site cg05575921 in this particular gene has been identified as the most reliable molecular signature of tobacco smoke exposure, enabling the addition of precision to risk models for lung cancer screening." (PMID 41302568, 2025). "While AHRR DNA hypomethylation is associated with increased lung cancer risk, AHRR is silenced by DNA hypermethylation in multiple human malignancies including breast, cervix, colon, lung, ovary and stomach, suggesting that it may exert tumor suppressive properties in these tumor entities." (PMID 37696456, 2023). "Although the association between AHRR hypomethylation and lung cancer has been replicated in several independent cohorts, it remains unknown whether altered AHRR methylation is causally involved in lung cancer development or represents an early response to tumor." (PMID 37691855, 2023). "For example, peripheral blood methylation at sites in the DNA annotated to genes such as AHRR (aryl hydrocarbon receptor repressor) has been shown to determine previous smoke exposure with much higher accuracy than cotinine levels and has been shown to predict future lung cancer risk." (PMID 32745538, 2020). "Higher expression is linked with some cancers (AHRR, DSC2), poorer prognosis of lung cancer (P2RY6), and cardiovascular diseases (GPR15, DCS2)." (PMID 40579423, 2025). "Hypomethylation of the top CpG, AHRR cg05575921, is a predictive biomarker of future lung cancer, with even proposed utility in population lung cancer screening." (PMID 38602535, 2024). "Data about the DNA methylation of the AhRR gene have recently been shown to provide eligibility criteria for screening those individuals, who are likely to develop lung cancer." (PMID 39199657, 2024). "Association between gene-level methylation scores (AHRR*, MYO1G, CYP1A1, FRMD4A, and GFI1*) and lung cancer risk, among ever smokers (186 matched pairs) nested in the CLUE II cohort (1989–2018)." (PMID 39544416, 2024). "Smoking exposure induced hypomethylation of AHRR and F2RL3, associated with increased lung cancer risk." (PMID 39440184, 2024). "Studies on epigenetic markers—particularly DNA methylation of pivotal genes such as F2RL3 and AHRR, as well as alterations in miRNA profiles affecting gene expression—have emerged as significant indicators for diagnosing and treating lung cancer." (PMID 39440184, 2024). "Understanding the role of the AhR/AhRR/CYP1A1 axis in lung cancer progression is of importance to improve current therapeutic approaches and develop new therapeutic strategies for the treatment of NSCLC." (PMID 39199657, 2024). "cg08238319 is annotated to the aryl hydrocarbon receptor repressor (AHRR) gene, and AHRR hypomethylation was correlated with an elevated risk of lung cancer." (PMID 39164771, 2024). "On the other hand, a large study employing mediation analysis in four prospective cohorts suggested that a considerable part (>30%) of the effect of smoking on lung cancer was mediated by changes in AHRR methylation." (PMID 37691855, 2023).
lung carcinoma (continued). "Aryl-hydrocarbon receptor repressor (AHRR) hypomethylation in peripheral blood is tightly linked with tobacco smoking and lung cancer." (PMID 37691855, 2023). "Well-established smoking-associated probes (e.g., cg14391737 within PRSS23 and cg05575921 within AHRR) associated with the incidence of COPD, lung cancer, ischemic heart disease, stroke, pain, and/or CKD." (PMID 37410739, 2023). "DNA hypomethylation in factor II receptor-like 3 (F2RL3) and aryl hydrocarbon receptor repressor (AHRR) gene is smoking-related biomarker in blood, which closely correlated with lung cancer incidence and mortality." (PMID 37391844, 2023). "Additional evidence shows that lower CpG cg05575921 methylation in AHRR (referred to as: AHRR CpG3 in the current study) predicts lung cancer and lymphoblastic leukemia." (PMID 34570895, 2022). "Of these, DNA methylation at cg05575921 in the AHRR gene has been found to be most strongly influenced by smoking in previous studies, but most restricted to lung cancer or chronic obstructive pulmonary disease." (PMID 34650928, 2021). "Our results did not support a causal effect of smoking-related DNA methylation in AHRR, F2RL3 and PRSS23 on the risk of lung cancer, which confirmed and extended the results from a recent MR study." (PMID 33729499, 2021). "The methylation status of the smoking markers AHRR and F2RL3 was highly associated with increased lung cancer risk." (PMID 32069786, 2020). "A low level of methylation at cg05575921 in the aryl-hydrocarbon receptor repressor (AHRR) gene is robustly associated with smoking, and some studies have observed associations between cg05575921 methylation and increased lung cancer risk and mortality." (PMID 32962699, 2020). "In bisulfite treated leukocyte DNA from 465 lung cancer patients from the Copenhagen prospective lung cancer study, we measured AHRR (cg05575921) methylation." (PMID 30730943, 2019). "Baseline characteristics of 465 patients with lung cancer by leukocyte DNA methylation of AHRR (cg05575921), quantiles." (PMID 30730943, 2019). "Cg05575921 (AHRR) methylation has also been identified as a potential biomarker for lung cancer and subclinical atherosclerosis in smokers." (PMID 30215712, 2019). "In lung tissue from subjects affected with lung cancer, we validated 3 of the 14 CpG sites in the intergenic region 2q37.1 (cg21566642 and cg05951221) and in the AHRR gene (cg05575921) at a Bonferroni-corrected P value of 3.57 × 10−3." (PMID 30342560, 2018). "Reversion of AHRR demethylation is a quantitative biomarker of smoking cessation, and AHRR methylation status is a quantifiable biomarker for lung cancer progress in smoking cessation." (PMID 28587272, 2017). "Our study confirmed the previous studies showing that hypomethylation of these AHRR and F2RL3 genes with respect to tobacco smoking was significantly associated with lung cancer risk in a Korean prospective cohort." (PMID 28453567, 2017). "Several epigenome-wide studies have consistently shown that the methylation levels of AHRR and F2RL3 were the top-ranked signals associated with tobacco smoking and smoking-related health risks such as lung cancer or cardiovascular disease." (PMID 28453567, 2017). "Here, we present data from four prospective cohort studies that convincingly demonstrate that hypomethylation in specific CpG sites of the AHRR and F2RL3 genes is associated with increased risk of subsequent lung cancer." (PMID 26667048, 2015). "A study employing Mendelian randomization suggested that low blood levels of AHRR methylation are not causally linked to lung cancer." (PMID 37691855, 2023). "Finally, lung cancer-specific mortality as well as overall mortality have been found to be elevated in individuals with low levels of AHRR methylation." (PMID 36621758, 2023).